BAP1 (BRCA1 associated deubiquitinase 1)
Diseases named in the same sentence as BAP1 in open-access papers (continued):
Sharing a sentence is not in itself a finding about the gene and the disease.
melanoma (continued). "Another research on melanoma illustrated the absence of BAP1 correlates with an increase in the activity of the NF-κB pathway." (PMID 37908350, 2023). "Together, these observations suggest that co‐induction of BAP1 deficiency and SF3B1 mutation suppresses melanoma cell growth independent of the GNAQ/11 mutation status." (PMID 34706158, 2022). "Eight other cases carried one or more mutations in genes also found in uveal or mucosal melanoma, but not in cutaneous melanoma: BAP1, SF3B1, or EIF1AX and hence were similarly suspect as misclassified." (PMID 34939927, 2021). "The presence of driver mutations such as BAP1 and SF3B1 has been shown to be strongly associated with metastasis and melanoma-specific mortality independent of GEP class." (PMID 34209210, 2021). "On the other hand, and admittedly small and limited in their size, reports support the notion that BAP1 is not expressed in melanoma arising in blue nevus, and state that it is also of aid in differentiating it from non-malignant blue nevi, as BAP1 expression is preserved in them." (PMID 40843873, 2025). "Furthermore, to determine whether BAP1 regulates the expression of MHC-II cluster genes in different cancer types, we depleted BAP1 in breast cancer cell line MDA-MB-231, brain tumor cell line KNS-42, and melanoma cell line MDA-MB-435s by CRISPR." (PMID 39817454, 2025). "In pigmented melanomas, unfavourable prognostic features such as: epithelioid cells (p = 0.0013), extrascleral extension (p = 0.027), macronucleoli (p = 0.0065), and the absence of BAP1 expression (p = 0.029) were statistically more frequently observed." (PMID 35681733, 2022). "Interestingly, we identified variants in five new candidate genes, i.e., ARID1A, ARID2, SMARCA4, PIK3R1 and BAP1, which neither have been previously identified in melanoma BM nor reported in CNS metastases from other cancers." (PMID 33578810, 2021). "Current treatments for patients with BAP1-inactivated melanoma are limited to conventional therapies used in other more common melanomas, which may not address the molecular mechanisms of these lesions entirely." (PMID 35052351, 2021). "Furthermore, we found three VUS’s in BAP1, of which one was novel and non-segregating in the family, and the E318K variant in MITF in one patient of a family with melanoma and RCC." (PMID 31034483, 2019). "A higher prevalence of germline mutations in BAP1 (not identified in our patients) and POT1 was also reported in a recent study by Pastorino and colleagues who identified seven carriers (2.6%) of mutations in each of these two genes among 273 Italian melanoma patients." (PMID 33050356, 2020). "While other genes (e.g. CDKN2C, CDKN2A, MITF, BAP1, PTEN, ERBB4, and FGFR2, etc.)are mutated with some frequency in melanoma, no common recurring mutations in these genes are observed or the function of observed mutations are unknown; therefore these genes were not included in our screen." (PMID 22536370, 2012). "Melanoma should always be considered in patients with BAP1-TPDS, even in the absence of classic gross, dermoscopic, histopathological, and molecular characteristics of typical melanoma." (PMID 34646590, 2021).
melanoma (continued). "Methylation of the genome of BAP1 was analyzed in melanoma, malignant mesothelioma, and RCC, but almost no decrease in BAP1 expression due to methylation was found." (PMID 30395583, 2018). "However, the identification of a potentially POT1 PV in a family diagnosed with multiple early-onset melanomas underscores the need for continued genetic screening in hereditary melanoma cases, especially when CDKN2A, CDK4, and BAP1 aberrations are absent." (PMID 40851494, 2025).
tumor predisposition syndrome (121 papers, 2016 to 2026). "For example, germline BAP1 missense variants are associated with both BAP1 tumor predisposition syndrome ( BAP1 -TPDS) and Küry-Isidor syndrome (KURIS), a rare neurodevelopmental disorder." (PMID 42238420, 2026). "BAP1 tumour predisposition syndrome (BAP1-TPDS) is a hereditary cancer syndrome caused by heterozygous pathogenic germline variants in BAP1." (PMID 41712014, 2026). "BRCA1-associated protein (BAP1) tumor predisposition syndrome (BAP1-TPDS) is a cancer syndrome caused by loss-of-function variants in the BAP1 tumor suppressor gene." (PMID 41551629, 2026). "The principal autosomal dominant syndromes account for most hereditary RCC: von Hippel–Lindau (VHL), Hereditary Leiomyomatosis and RCC (HLRCC), Hereditary Papillary RCC (HPRC), Birt–Hogg–Dubé (BHD), and BAP1 tumor predisposition syndrome (BAP1-TPDS)." (PMID 41440226, 2025). "Pathogenic germline variants in BRCA1-Associated Protein 1 (BAP1) gene underlie BAP1 tumor predisposition syndrome, characterized by a multiorgan tumorigenesis with meningeal involvement." (PMID 40469416, 2025). "BAP1 germline mutations have been connected with tumor predisposition syndrome (TPDS), predisposing patients mainly to melanoma and mesothelioma." (PMID 40075786, 2025). "The incidence of renal cell carcinoma (RCC) in families with BAP1 tumor predisposition syndrome (TPDS) is significantly increased; genetic counseling and customized monitoring are advised for suspicious families." (PMID 41440218, 2025). "Rare cases are caused by germline mutations of the BRCA1-associated protein 1 (BAP1) gene as part of the BAP1 tumour predisposition syndrome." (PMID 41147025, 2025). "While the majority of BIMT cases are sporadic and exhibit an indolent course, their occurrence in the context of a germline BAP1 variant suggests a higher risk for a hereditary condition known as BAP1 tumor predisposition syndrome (BAP1-TPDS)." (PMID 40558591, 2025). "Loss of BAP1 is implicated in several cancers, in the familial cancer syndrome BAP1 Tumor Predisposition Syndrome, and in the neurodevelopmental disorder Küry-Isidor syndrome." (PMID 41022584, 2025). "Germline BAP1 mutations are attributed to an inherited genetic disorder known as BAP1 tumor predisposition syndrome (BAP1-TPDS)." (PMID 41160198, 2025). "BAP1 tumor predisposition syndrome (BAP1-TPDS) is an autosomal dominant disorder caused by germline alterations in the tumor suppressor gene BAP1." (PMID 40558302, 2025). "BAP1‐inactivated melanocytic tumours (BIMTs) occur sporadically and in association with a familial tumour predisposition syndrome involving germline mutations in the BRCA1‐associated protein‐1 (BAP1) gene." (PMID 39976080, 2025). "The BAP1 tumor predisposition syndrome (BAP1-TPDS) is caused by heterozygous germline mutations in the BRCA1-associated protein-1 gene (BAP1)." (PMID 40867321, 2025). "BAP1-associated tumor predisposition syndrome is a rare disease that is primarily associated with mesothelioma and uveal melanoma." (PMID 38390862, 2024). "BAP1-Tumor Predisposition Syndrome (BAP1-TPDS) is an autosomal dominant disorder caused by variants in the BAP1 gene." (PMID 38824259, 2024). "BAP1-Tumor Predisposition Syndrome (TPDS) is caused by germline variants in BAP1 and predisposes to solid tumors." (PMID 38824259, 2024). "Pathogenic germline variants in BRCA1-Associated Protein 1 (BAP1) cause BAP1 tumor predisposition syndrome (BAP1-TPDS)." (PMID 37956408, 2024). "Pathogenic germline variants in the BRCA1-Associated Protein 1 (BAP1) tumor suppressor gene cause a rare, life-threatening tumor predisposition syndrome (BAP1-TPDS, OMIM 614327) also known as BAP1 cancer syndrome as the majority of carriers develop malignancy." (PMID 37956408, 2024). "Familial aggregation of UM is rare and can occur as part of the tumor predisposition syndrome BAP1-TPDS." (PMID 35920959, 2023).
tumor predisposition syndrome (continued). "Risk factors associated with the UM development include fair skin colour, light-coloured irises (blue or grey), tendency to sunburn, congenital atypical mole syndrome, ocular melanocytosis (nevus of Ota), or BAP1/MBD4-tumour predisposition syndrome." (PMID 38087265, 2023). "Among them was one patient who had subsequently been diagnosed with BAP1 tumor predisposition syndrome (patient #4)." (PMID 36641486, 2023). "BAP1 mutations comprise a syndrome, the BAP1 tumor predisposition syndrome, with an increased risk of developing skin, kidney, eye, and mesothelial tumors." (PMID 37542187, 2023). "Germline pathogenic variants (GPV, including likely pathogenic variants) in BAP1 have subsequently been associated with a variety of tumours resulting in the recognition of BAP1-associated tumour predisposition syndrome (BAP1-TPDS)." (PMID 37607989, 2023). "Because of common co-existence with cutaneous melanoma and breast cancer many reports direct attention to BAP-1 tumour predisposition syndrome (BAP1-TPDS)." (PMID 38087265, 2023). "BAP1 is also causally linked to a BAP1 tumor predisposition syndrome, characterized by increased susceptibility to MMe, uveal and cutaneous melanomas, benign melanocytic tumors, and several other cancers." (PMID 37479714, 2023). "Question 2: The BAP1 gene is significant for its pathogenesis in BAP1-tumor predisposition syndrome." (PMID 38090659, 2023). "The Carney complex, DICER1 syndrome, familial paraganglioma syndromes, BAP1 tumor predisposition syndrome, and familial retinoblastoma have also been covered in other WHO classification schemes for endocrine, skin, and eye tumors." (PMID 35969220, 2022). "Loss of functional BAP1 can lead to tumorigenesis due to acquired genetic alterations or in the setting of BAP1 cancer syndrome (also referred to as the BAP1-tumor predisposition syndrome)." (PMID 35381901, 2022). "BRCA-1-associated protein-1 (BAP1) tumour predisposition syndrome (BAP1-TPDS) is a dominant hereditary cancer syndrome." (PMID 36148247, 2022). "Breast cancer susceptibility gene 1 associated protein 1 (BAP1) tumor predisposition syndrome is an autosomal dominant syndrome associated with increased risk of malignant mesothelioma, uveal melanoma, cutaneous melanoma, basal cell carcinoma, and RCC." (PMID 36011051, 2022). "Individuals with BAP1 gene mutation tend to develop an inherited disorder known as the BAP1 tumor predisposition syndrome, which makes them susceptible to various cancers including MM." (PMID 36012262, 2022). "BAP1 tumor predisposition syndrome is caused by pathogenic germline variants in the BAP1 tumor suppressor gene and characterized by a predisposition to various tumors including meningioma." (PMID 35969220, 2022). "BRCA-1 associated protein 1 (BAP1) tumour predisposition syndrome (TPDS) is a hereditary condition characterised by germline mutation of the tumour suppressor BAP1." (PMID 35992853, 2022). "BAP1 (BRCA1-associated protein,) mutations resulting in loss of BAP1 and loss of nuclear expression have been reported both in rhabdoid and papillary meningioma and can be associated with BAP1 tumor predisposition syndrome." (PMID 36230612, 2022). "The pathogenesis of UM has not been fully elucidated, but well-defined risk factors include a light iris, fair skin, cutaneous nevi, iris nevi, dysplastic nevus syndrome, and BRCA1-associated protein-1 (BAP1) tumor predisposition syndrome." (PMID 36157683, 2022). "BAP1 tumor predisposition syndrome is associated with UM, malignant mesothelioma, cutaneous melanoma, renal cell carcinoma, basal cell carcinoma, hepatocellular carcinoma, cholangiocarcinoma, and meningioma." (PMID 34771666, 2021). "Her screening regimen consists of a combination of the recommendations for BAP1 Tumor Predisposition Syndrome and Lynch Syndrome, respectively." (PMID 33541411, 2021).
tumor predisposition syndrome (continued). "Germline BAP1 mutations increase susceptibility to a wide spectrum of cancers, the so-called BAP1 tumor predisposition syndrome (BAP1-TPDS)." (PMID 34356093, 2021). "Rare genetic syndromes such as BAP1 tumor predisposition syndrome are at risk of ascertainment bias, where unaffected carriers or carriers with unusual clinical presentation are less likely to be captured." (PMID 34771666, 2021). "Germline mutations in the tumor suppressor gene BAP1, encoding the BRCA1 associated protein-1 (BAP1), cause the so-called BAP1 tumor predisposition syndrome (BAP1-TPDS), characterized by an increased propensity to develop several types of cancer." (PMID 35008179, 2021). "Such rare combinations and absence of asbestos exposure in the present case raised the possibility of the tumor being associated with BAP1 germline alterations (BAP1 tumor predisposition syndrome)." (PMID 34333253, 2021). "Germline pathogenic variants in the BRCA1-associated protein-1 (BAP1) gene cause the BAP1 tumor predisposition syndrome (TPDS)." (PMID 32218990, 2020). "Not only UM was described in these families but other cancers such as cutaneous melanoma and renal cell carcinoma were present in family members with this BAP1 tumor predisposition syndrome (BAP1-TPDS)." (PMID 33396957, 2020). "BRCA1-associated protein 1 (BAP1) tumor predisposition syndrome (BAP1-TPDS) is associated with a germline mutation of the BAP1 gene on 3p21.1." (PMID 33194703, 2020). "BAP1-inactivated nevus (BAPoma) is a relatively new entity of an atypical spitzoid tumor, and can serve as an early sign of BAP1 tumor predisposition syndrome." (PMID 32429485, 2020). "A genetic risk factor is the presence of a germline mutation in the BAP1 gene, which is associated with the BAP1-tumor predisposition syndrome." (PMID 32998469, 2020). "BAP1 mutations are often described as cancer drivers, most notably in the case of BAP1 tumour predisposition syndrome (BAP1-TPDS;)." (PMID 33105797, 2020). "The mode of inheritance in BAP1 tumour predisposition syndrome is autosomal dominant and a majority of the germline pathogenic variants in BAP1 are truncating." (PMID 33240524, 2020). "Another study found that among 181 families afflicted with BAP1-tumor predisposition syndrome, there were 140 unique germline variants in the BAP1 gene." (PMID 32197306, 2020). "The BAP1 tumor predisposition syndrome caused by germline BAP1 mutations is not only associated with cutaneous melanoma." (PMID 32429485, 2020). "The BAP1-tumor predisposition syndrome is the most studied genetic condition associated with MPM development and is caused by mutations in the BRCA1-associated protein 1 (BAP1) gene." (PMID 32318342, 2020). "Individuals that inherit one inactive BAP1 allele (BAP1 tumour predisposition syndrome) have significantly higher predisposition to cancer." (PMID 30669483, 2019). "Germline pathogenic variants in the BRCA1-associated protein-1 (BAP1) gene underlie the BAP1-tumor predisposition syndrome (BAP1-TPDS, OMIM 614327)." (PMID 31382694, 2019). "Germline pathogenic variants in the BRCA1-associated protein-1 (BAP1) gene cause the BAP1-tumor predisposition syndrome (BAP1-TPDS, OMIM 614327)." (PMID 31382694, 2019). "BRCA1 associated-protein 1 (BAP1) tumor predisposition syndrome is associated with an increased risk for malignant mesotheliomas, uveal and cutaneous melanomas, renal cell carcinomas, and singular cutaneous lesions." (PMID 31706282, 2019). "BAP1 is a tumour suppressor gene which has been implicated in an autosomal dominant hereditary tumour predisposition syndrome associated with heterozygous germline mutation." (PMID 26982343, 2016). "BAP1 germline mutations are observed in 9–12% of PM patients, although more commonly detected in younger-age patients and in patients with tumors related to BAP1 tumor predisposition syndrome." (PMID 40361508, 2025). "Germline mutations in BAP1 also lead to a BAP1 Tumor Predisposition Syndrome (BAP1-TPS)." (PMID 41022584, 2025).